VEGFA (vascular endothelial growth factor A)
Diseases named in the same sentence as VEGFA in open-access papers (continued):
Sharing a sentence is not in itself a finding about the gene and the disease.
tumor (continued). "Furthermore, VEGFA expression is correlated with tumor stage and progression." (PMID 29104726, 2017). "This drug inhibits the formation of tumor blood vessels induced by vascular endothelial growth factor A (VEGF-A); increases T cell infiltrations; reverses expression of inhibitory molecules associated with T cell exhaustion; and may directly mediate antitumor effect." (PMID 29163521, 2017). "VEGFA may act as a potential therapeutic target for tumor stem-like cells of prolactinomas." (PMID 28163656, 2017). "Moreover, VEGFA suppresses immune-mediated anti-tumour responses in EOC53." (PMID 28383032, 2017). "Besides VEGFA, miR-29c may target multiple genes and pathways to inhibit tumor growth and metastasis, implicating miR-29c as a novel promising therapeutic target to provide clinical benefit." (PMID 28241836, 2017). "Thus, VEGFA increases tumor‐initiating OVCA cell abundance in vivo and this is Bmi1 dependent." (PMID 28179359, 2017). "Therefore, VEGFA may be required for the function of miR-1 in inhibiting tumor growth and metastasis." (PMID 27777493, 2016). "Furthermore, VEGFA signaling from TEMs modulated vascular junctions and tumor cell intravasation." (PMID 26910374, 2016). "In fact, neutrophils expressing VEGFa could be found in the microvessels of the endometrium during the proliferative stage of the cycle when the endometrium can quadruple in thickness, which suggest the potential impacts of neutrophil secreted VEGFa in tumor progression." (PMID 26079540, 2015). "Consequently, lactate induces the expression of several HIF-1 target genes, among which vascular endothelial growth factor A (VEGFA) in normoxic oxidative tumor cells and VEGF receptor-2 (VEGFR2) in normoxic endothelial cells and macrophages are key contributors to lactate-induced angiogenesis." (PMID 26528183, 2015). "Therefore, we hypothesize that miR-410 might mediate a similar effect on VEGFA expression in RNV, given that tumor growth and RNV both share the trait of abnormal blood vessel growth closely associated with VEGFA overexpression." (PMID 24777200, 2014). "Therefore downregulated expression of CCL2 and VEGFA following AhR knockdown may decrease the blood supply necessary for tumor growth." (PMID 24932473, 2014). "Therefore, the opposite effect of TGF-beta on VEGFA expression could contribute to its differential role as tumor suppressor or tumor promoter in different cell context." (PMID 23536895, 2013). "The FDA‐approved anti‐VEGFA antibody, bevacizumab (BEV), can counteract VMP1's tumor‐promoting effect in GBM." (PMID 41589276, 2026). "VEGFA secreted by cancer cells activates VEGFR2 on vascular endothelial cells (VECs), driving endothelial proliferation, tumour angiogenesis, and LUAD progression." (PMID 41481002, 2026). "This co-regulation of VEGFA and HBEGF likely enhances vascular remodeling and tumor progression through complementary pathways, further reinforcing ICB resistance." (PMID 41514936, 2026). "Among them, VEGFA and HBEGF are known to exert central roles in driving tumor angiogenesis, while CXCL8 and its related chemokines positively regulate angiogenic processes." (PMID 41514936, 2026). "Within the tumor microenvironment (TME), exosome-derived ZFAS1 remodels intercellular communication networks, promoting angiogenesis via STAT3/VEGFA signaling, though its immunometabolic regulatory mechanisms warrant further elucidation." (PMID 41450817, 2026). "These macrophages are activated by hypoxia and release factors such as VEGFA and HBEGF that promote new blood vessel formation and tumor growth." (PMID 41514936, 2026). "Treatment with bevacizumab, a monoclonal antibody against VEGFA, significantly inhibited VMP1‐driven tumor growth and prolonged survival in mice." (PMID 41589276, 2026).
tumor (continued). "Angiogenesis mediated by vascular endothelial growth factor A (VEGF-A) is essential for physiological vascular remodeling but also drives pathological processes, including tumor growth, ocular neovascularization, and inflammation." (PMID 42117522, 2026). "c MET upregulates VEGFA, under hypoxic conditions via hypoxia inducible factor-1 (HIF-1), which promotes angiogenesis necessary for tumour growth." (PMID 41476776, 2026). "VEGFA facilitated the proliferation of responder tumor subcluster cells, whereas VEGFC secreted from non‐responder tumor cells interacted with tumor microenvironment cells." (PMID 40843133, 2025). "To determine the contribution of prominent vascular growth factor, VEGFA, on the observed microvascular remodeling of the viable tumor post-SA-HFIRE, we measured gene expression of the tumor and fat pad using real-time quantitative PCR (RT-qPCR)." (PMID 39998766, 2025). "On the other hand, we found an enrichment of hypoxia related terms for NMF_4 and NMF_5 with the top genes VEGFA, NDRG1, and ENO1, markers of previously reported “MES-hypoxia” tumor cell state." (PMID 40781324, 2025). "Bevacizumab, a humanised monoclonal antibody, blocks all known isomers of vascular endothelial growth factor A (VEGF-A) and suppresses tumour angiogenesis." (PMID 40496305, 2025). "Both VEGFA and VEGFC inhibition effectively suppressed tumor growth, suggesting that VEGF signaling complexity hampers the response to ABCP." (PMID 40843133, 2025). "The results demonstrated a significant overexpression of VEGFA, CD31 (a vascular marker), and CD133 (a marker for human hematopoietic precursor and EPC cells) in A549-PM xenograft tumor tissues compared to A549-Par tissues." (PMID 40940965, 2025). "Anti-angiogenic control is provided by miR-138-5p (HIF-1α/VEGFA blockade) and miR-101, which thwarts vascular mimicry by targeting TGFβR1/SMAD2 in tumor cells and SDF1 in CAFs." (PMID 41007803, 2025). "Circ4207 alleviates the suppressive effects of miR‐20b‐5p on VEGFA expression in CRC, leading to enhanced invasion, angiogenesis, and tumor growth." (PMID 40356340, 2025). "The CCK8 assays showed exogenous TGF‐β1 and VEGFA rendered tumor cells resistant to RT, while the blockade of TGF‐β1 and VEGFA with Y332D significantly inhibited survival fractions and proliferation of 4T1, CT26, H22, and GL261 tumor cells under irradiation." (PMID 40470716, 2025). "Studies have shown that increased TGF-β1 and vascular endothelial growth factor-A (VEGF-A) promote angiogenesis and extracellular matrix formation around tumor cells." (PMID 40407940, 2025). "The content of several angiogenic and proinflammatory factors, including VEGFA and FGF2, was reduced in other SHP2-silenced tumor cells from culture and the tumors they generated." (PMID 40131370, 2025). "Overall, we conclude that YOD1 acts as a tumor suppression factor by attenuating tumor growth and metastasis through the ZNF24/VEGFA pathway in ccRCC." (PMID 40274778, 2025). "MiR-hsa-125b-5p affects cell proliferation, migration, and invasion by targeting multiple tumor suppressor genes such as CD147 and TPD52, and it participates in cancer progression by targeting STAT3, BMPR1B, VEGFA, SphK1, CDKN2A, and Sema4D." (PMID 41361055, 2025). "RNA-Seq analysis identified VEGFA as a key gene downregulated by FTO, implicating its role in angiogenesis and tumor progression." (PMID 40316995, 2025). "TGF-β1 activates the SMAD3 and ERK1/2 signaling pathways, inducing neutrophils in the tumor microenvironment to express tumor-promoting factors, such as OSM and VEGFA mRNA, thereby converting neutrophils into a pro-tumor phenotype." (PMID 40564191, 2025). "These resistant TAMs preferentially express angiogenic (VEGFA) and immunosuppressive (CD274, ARG1) genes and promote tumor vascularization." (PMID 41450739, 2025).
tumor (continued). "In summary, RBM15 drives HCC progression by enhancing angiogenesis through VEGFA stabilization and by mediating HBx-induced circRNA degradation, collectively establishing RBM15 as both a tumor promoter and a potential therapeutic target in liver cancer." (PMID 41403702, 2025). "By emphasizing the therapeutic potential of targeting VEGFA or host macrophages, our study identifies routes to optimize CAR T-cell therapy outcomes in hematologic malignancies via tumor microenvironment manipulation." (PMID 39998425, 2025). "After the SH intervention, the levels of the tumor angiogenesis-related genes MMP-2, VEGFA, VEGFC, VAV2, and LARP1 were significantly downregulated when compared with the Model group, whereas the GADD45A level was markedly upregulated." (PMID 41444284, 2025). "Another interesting observation here is the presence of signaling by the VEGF pathway, which involved two upregulated genes (KDR, VEGFA) and three downregulated genes (NRP1, PRKACB, ROCK1) in G2 tumor AOIs compared to G1." (PMID 39245631, 2025). "This, in turn, triggers VEGFA and MMP9 expression, facilitating tumor-induced lymphangiogenesis and LN metastasis." (PMID 40739091, 2025). "Tumor endothelial cells (ECs) in CRC undergo transcriptional reprogramming toward a pro-angiogenic phenotype, upregulating VEGFA-VEGFR2 signaling and ECM genes (e.g., COL4A1, SPARC) while downregulating antigen presentation molecules (MHC I/II)." (PMID 41450739, 2025). "Collectively, these results show that SPP1hi Mφs and VEGFAhi neutrophils colocalize with APLNhi tip cells to form an angiogenic niche, and that these myeloid subtypes actively engage in modulating the tumor vasculature by expressing ADM and VEGFA." (PMID 41203997, 2025). "Vascular endothelial growth factor A (VEGFA) is highly expressed in HCC and promotes tumor vascularization." (PMID 41403702, 2025). "The VEGF protein family consists of VEGFA, VEGFB, VEGFC, VEGFD, and many others, some members of which are inducers of tumor lymphangiogenesis." (PMID 39866224, 2025). "To further verify the necessity of VEGFA in NAT10-mediated angiogenesis and abnormal tumor vascularization, we transfected NAT10-knockdown GC cells with VEGFA expression plasmids." (PMID 40860183, 2025). "Hypoxia triggered by anti-VEGF therapy increases galectin-1 expression in tumor cells, where it binds glycosylated VEGFR2 on endothelial cells to sustain angiogenesis through VEGFA-mimetic signaling." (PMID 40693266, 2025). "CAFs-derived MMPs degrade the ECM that allows VEGFA to interact with vascular endothelial growth factor receptor (VEGFR), thus promoting tumor angiogenesis." (PMID 40248695, 2025). "the results of the scratch assay and transwell assay showed that after antagonizing the downregulation of VEGFA by FTO in HCCLM3 cells, tumor invasiveness and migratory capacity were significantly upregulated." (PMID 40316995, 2025). "The level of VEGFA, which is induced 177-fold in CM from BCAM-overexpressing (BCAM-OE) tumor cells, showed a significant correlation with the concentration of soluble BCAM (Pearson r = 0.51; p = 5.6 × 10− 6)." (PMID 40082910, 2025). "VEGFA was, as expected, elevated in GPR65 KO compared with m.CR tumor cells and was significantly diminished after FOXO1 KO." (PMID 39998425, 2025). "This aligns with evidence that high APOC1 expression enhances the secretion of cytokines, such as EGF, PDGF, VEGFA, IL-1, IL-8, TNF-α, MMP-9, MMP-2, and NO, which collectively drive tumor cell proliferation, invasion, and angiogenesis." (PMID 39873475, 2025). "Bevacizumab, a current drug targeting VEGFA, has been approved as part of immunotherapeutic combinations for HCC and has demonstrated remarkable anti-tumor efficacy." (PMID 39546272, 2025). "VEGFA, a key factor in angiogenesis, is highly expressed in TAM subgroups that promote tumor growth by enhancing endothelial cell proliferation and migration." (PMID 40055311, 2025).
tumor (continued). "A cascade of pro-tumorigenic factors, including IL6, VEGFA, IL11, PDGFA, and CXCL12, further amplify the formation of complex microenvironments that support tumor cell colonization and proliferation, exacerbating the progression of CRLM." (PMID 39979806, 2025). "Vascular endothelial growth factor A (VEGF-A), secreted by tumor cells, binds to the transmembrane tyrosine kinase receptors VEGFR-1 and VEGFR-2 on endothelial cells, thereby inducing angiogenesis in solid tumors." (PMID 40382743, 2025). "The vascular endothelial growth factor-A (VEGF-A) is considered to be an important angiogenic promoter and is believed to be a potential target for tumor chemoprevention and treatment." (PMID 40414997, 2025). "In contrast, the expression levels of STAT3 downstream target genes—such as VEGFA, IL-6, MMP13, Bcl2, and Twist1—remained comparable across all experimental groups, likely due to tumor excision occurring at a stage when metastasis was already underway." (PMID 40806360, 2025). "Some works confirmed that the PI3K/AKT regulates numerous pro-angiogenic cytokines, including VEGFA and MMP9, which are involved in tumor angiogenesis." (PMID 40443670, 2025). "Complementing this, m6A “reader” IGF2BP proteins stabilize pro-angiogenic transcripts such as VEGFA and EPHA2, and exosomal transfer of IGF2BP2 from tumor cells can activate endothelial PI3K–AKT signaling to drive vessel formation and metastatic spread." (PMID 41280938, 2025). "Tumor-derived VEGFA and TGFβ2 signals were received by NRP2 and TGFβR2/3 receptors present on MES and RG-PC cells, respectively, with PDGFA_PDGFRA signaling from tumor cells directing final PC specification." (PMID 40562749, 2025). "Subsequently, M2 macrophages can secrete pro-angiogenic factors such as VEGFA and MMP9, thus promoting tumor angiogenesis." (PMID 40612677, 2025). "Among pro-tumor TAM subsets, angiogenesis-related genes, such as SPP1 and VEGFA were identified in TAMs." (PMID 40050933, 2025). "PCD-1 significantly blocked angiogenesis in the tumour plugs, as confirmed by CD31 and VEGFA IHC staining." (PMID 40435846, 2025). "As mounting evidence highlights the vital role of VEGFA in tumor angiogenesis, we subsequently examined the connection between SLC9A2 and VEGFA." (PMID 40474298, 2025). "CAF release pro-angiogenic factors such as VEGFA, PDGFC, and FGF2 to stimulate or adversely affect angiogenesis in tumor tissues." (PMID 40485724, 2025). "We found that the signaling of VEGFA-VEGFR1, VEGFA-VEGFR2, MIF-(CD74 + CXCR4) and MIF-(CD74 + CD44) was significantly increased in the high-risk state; whereas the signaling of LGALS9-CD45, LGALS9-CD44, and IL1B-IL1R2 was decreased, which may affect the tumor cell adhesion and migration." (PMID 40563096, 2025). "The upregulation of vascular endothelial growth factor A (VEGF-A), a protein that promotes neoangiogenesis, enhances tumor angiogenesis, thereby providing additional nutrients and oxygen to support tumor growth." (PMID 40530008, 2025). "EIF4A3‐induced circ_0059914 upregulates VEGFA by sponging miR‐1249 to increase EMT, angiogenesis, and tumor growth in glioma." (PMID 40356340, 2025). "In summary, our single-cell analysis identified a clinically relevant VEGFA+TC subpopulation characterized by EMT activation and heightened metastatic capacity, providing new insights into CRC tumor heterogeneity and progression." (PMID 40574852, 2025). "Hypoxia-induced expression of VEGFA potentiates the ability of interleukin-10 (IL-10) and prostaglandin-E2 (PGE2) to drive expression of Fas ligand (FasL) on tumor ECs to selectively induce apoptosis of cytotoxic T cells but leave Treg cells unscathed." (PMID 39567756, 2025). "This enhancement is mediated through the activation of signaling axes such as TGF-β, VEGFA, and LGALS9-HAVCR2, thereby facilitating immune evasion and promoting tumor angiogenesis." (PMID 41252877, 2025).
tumor (continued). "In PAK1KD tumours, a marked reduction in CD31 with an unchanged CD34 expression suggests suppressed angiogenesis, which is consistent with reduced VEGFA levels." (PMID 41294859, 2025). "Molecular mechanisms were analyzed via Western blot (PTEN, p-AKT, VEGFA), co-immunoprecipitation (PTEN ubiquitination), and in vivo nude mice study to detect the role of USP13 in tumor angiogenesis." (PMID 40746889, 2025). "ETS1, GSK3β, VEGFA, and YWHAZ were significantly upregulated in tumor tissues (p < 0.001), indicating their oncogenic roles in HNC progression." (PMID 39518147, 2024). "Cytokines and chemokines, such as VEGFA, TGF-β, and TNF-α, are released by tumor cells, stromal cells, and immune cells, and they regulate PMNs of distant organs, making them suitable for the metastatic growth of cancer cells recruited." (PMID 38590651, 2024). "For CD14+ monocytes, the VEGFA/PGF-VEGFR1 axes play a significant role in tumor angiogenesis, and the EREG/AREG-EGFR communications serve as a critical factor in tumor proliferation in several solid human cancers." (PMID 38600248, 2024). "As GBM is a hyperemic tumor with high expression of VEGF, VEGFA is a reasonable target molecule in the treatment of GBM." (PMID 39295944, 2024). "Various studies have reported that VEGFA and VEGFB expression is higher in malignant tissues than in normal oral mucosa, and they play a significant role in enhancing angiogenesis and tumour growth in OSCC." (PMID 38426619, 2024). "In this study, a significant increase in PTGS2 with VEGFA, KDR, CXCR1 and CXCR2 expression was observed in tumour samples compared to their paired normal samples, with the exception of VEGFB, whose expression was not statistically significant." (PMID 38426619, 2024). "Recurrent samples were enriched in mesenchymal-like tumor cells (“MES”), expressing high levels of NDRG1 and VEGFA that further distinguish them as hypoxic." (PMID 38805346, 2024). "A recent single-cell study of MCs across cancers divided tumor MCs into two subtypes: protumorigenic MCs, characterized by a low TNF+/VEGFA+ ratio, and antitumorigenic MCs, characterized by a high TNF+/VEGFA+ ratio." (PMID 39840068, 2024). "Meanwhile, overexpressed of LAMC2 increased the level of VEGFA and p-AKT in xenograft tumor tissues." (PMID 38989468, 2024). "Ligand-receptor analysis uncovered several significant interaction channels, including ligands that were distinctively upregulated in the tumor cells such as CD24, VEGFA, DLL3, and DLK1." (PMID 38358826, 2024). "Meanwhile, VCAM1 and VEGFA were specifically expressed in cells of cluster EC2 and those of cell state 2, indicating that they were tumor cells." (PMID 39301023, 2024). "This process is exacerbated by the overproduction of VEGFA and PGE2, which further induce FasL expression on tumor cells." (PMID 39769351, 2024). "Then, a Western blot analysis was performed to detect the expression of VEGFA and γH2ax, and the results also showed that carboxy-PTIO rescued the DNA damage level and inhibitory effect of tumor vascularization." (PMID 38750472, 2024). "Other studies have pointed out that TWEAK/Fn14 signals can significantly regulate vascular endothelial growth factor (VEGF), with TWEAK able to induce tumor angiogenesis by stimulating Fn14 and inducing VEGFA directly and indirectly." (PMID 39166480, 2024). "It was also found that in TAMs, hypoxia-inducible factor-1 (HIF-1α), during oxygen deprivation, activated vascular endothelial growth factor A (VEGF-A), involved in tumor blood vessel neogenesis." (PMID 39410029, 2024). "Bevacizumab (Bev) is the most common form of anti-angiogenic agent in the United States, which acts by binding to and inhibiting vascular endothelial growth factor A (VEGF-A) and thus hindering the development of tumor vasculature." (PMID 38372901, 2024).